RNU6-716P (RNA, U6 small nuclear 716, pseudogene)
Gene: Small nuclear RNA gene on chromosome 1 (200,008,505 to 200,008,607, reverse strand). Ensembl gene ENSG00000202491.
Homologues: Orthologues: chimpanzee U6 (96% identical), macaque U6 (92% identical), dog U6 (65% identical), rabbit U6 (63% identical), guinea pig U6 (51% identical). Paralogues in human: RNU6-1011P (80% identical), RNU6-536P (80% identical), RNU6-552P (80% identical), RNU6-73P (80% identical), RNU6-1020P (79% identical), RNU6-1029P (79% identical), RNU6-12P (79% identical), RNU6-13P (79% identical), RNU6-16P (79% identical), RNU6-21P (79% identical), RNU6-31P (79% identical), RNU6-32P (79% identical), and 1286 more.